CTHRC1 (collagen triple helix repeat containing 1)
Diseases named in the same sentence as CTHRC1 in open-access papers (continued):
Sharing a sentence is not in itself a finding about the gene and the disease.
hepatocellular carcinoma (26 papers, 2013 to 2025). A malignant tumor that arises from hepatocytes. "Similar to studies of hepatocellular carcinoma, approximately 30.8% of all patients showed high expression of CTHRC1 and this was associated with a lower 10-year overall and disease-free survival rates." (PMID 26214021, 2015). "CTHRC1 is highly expressed in hepatitis B virus- (HBV-) associated hepatocellular carcinoma." (PMID 32848510, 2020). "CTHRC1 promotes hepatocellular carcinoma cell invasion by activating the RhoA/Rho-associated kinase (ROCK) pathway and facilitates adhesion of hepatocellular carcinoma cells to ECM through induction of integrin β1 expression and activation of focal adhesion kinase (FAK)." (PMID 32848510, 2020). "For example, collagen triple helix repeat containing-1 (CTHRC1) plays a significant role in modulating cell proliferation and invasion in hepatocellular carcinoma (HCC), potentially through mechanisms related to DNA methylation." (PMID 39839798, 2024). "It is frequently detected in several solid tumors that the expression of CTHRC1 is high, such as breast ductal carcinoma, hepatocellular carcinoma, gastric cancer, colorectal cancer, and melanoma." (PMID 35246517, 2022). "In hepatocellular carcinoma, supressing CTHRC1 expression can inhibit integrin β, and thereby inhibiting cell migration and invasion and inducing apoptosis." (PMID 35300110, 2022). "CTHRC1 regulates the occurrence and development of cervical, pancreatic and liver carcinoma by participating in cell proliferation, cell migration, type I collagen synthesis and damaged vascular repair." (PMID 35300110, 2022). "Another study of hepatocellular carcinoma suggests that CTHRC1 inhibits anoikis and increases tumor cell survival by activating integrin β expression." (PMID 32848510, 2020). "CTHRC1 promotes invasiveness and metastasis of hepatocellular carcinoma through the activation of PI3K/protein kinase B (PKB)/AKT/ERK/cAMP response element-binding protein (CREB) signaling pathway, which induces EMT change and MMP2/MMP9 expression." (PMID 32848510, 2020). "And miR-98 dramatically downregulates CTHRC1 by directly targeting the 3′-UTR of CTHRC1 suppressing hepatocellular carcinoma formation." (PMID 32848510, 2020). "In hepatocellular carcinoma, CTHRC1 downregulates miR-155-5p through the activation of GSK-3β-involved Wnt/β-catenin signaling to promote tumor formation." (PMID 32848510, 2020). "Overexpression of CTHRC1 in hepatocellular carcinoma contributes to tumor invasion and predicts worse prognosis." (PMID 29285247, 2017). "In hepatocellular carcinoma CTHRC1 promotes cell adhesion through activation of integrin β1 and phosphorylation of focal adhesion kinase (FAK), while the activation of RhoA, but not Rac1 or Cdc42 plays a crucial role." (PMID 27430622, 2016). "Using microarray analysis, we found that the CTHRC1 gene is overexpressed in hepatocellular carcinoma (HCC)." (PMID 23922981, 2013). "In the present report, we show that CTHRC1 plays an important role in migration and invasion of hepatocellular carcinoma and that overexpression of CTHRC1 predicts poor prognosis in patients with HCC." (PMID 23922981, 2013). "Moreover, CTHRC1 was demonstrated that overexpressed in hepatocellular carcinoma tissues significantly correlating with poor survival rate, which can be used as a prognostic marker for liver cancer." (PMID 35004767, 2021).
hepatocellular carcinoma (continued). "Previous studies have demonstrated that CTHRC1 activates HIF-α pathway and contributes to tumor angiogenesis in hepatocellular carcinoma and pancreatic cancer." (PMID 35928443, 2022). "In addition, CTHRC1 promotes cell migration and adhesion through regulation of the Src/FAK signaling pathway in pancreatic cancer and integrinβ1 in hepatocellular carcinoma." (PMID 32156314, 2020). "CTHRC1 has been reported to be highly expressed in pancreatic cancer and hepatocellular carcinoma, but neither the role of Ror2 or CTHRC1 has been studied in UC." (PMID 28427201, 2017). "There are reports of CTHRC1, which could accelerate migration and adhesion by upregulating the expression of the integrin β family, and the phosphorylation of focal adhesion kinase (FAK) in ovarian cancer, hepatic carcinoma, and pancreatic cancer; however, it has not been found in lung cancer yet." (PMID 35246517, 2022).
pulmonary fibrosis (25 papers, 2017 to 2026). Chronic progressive interstitial lung disorder characterized by the replacement of the lung tissue by connective tissue, leading to progressive dyspnea, respiratory failure, or right heart failure. "In COVID-19 fatalities, lung analyses have revealed inflammation-associated AT2 cell states that hinder proper regeneration, coupled with pathogenic fibroblasts expressing CTHRC1, possibly driving rapid pulmonary fibrosis progression." (PMID 38891078, 2024). "This review highlights recent studies suggesting that CTHRC1 can serve as a diagnostic and prognostic biomarker for fibrosis in idiopathic pulmonary fibrosis, systemic sclerosis, and post-COVID-19 lung fibrosis." (PMID 38891078, 2024). "CTHRC1 (collagen triple helix repeat containing 1) is a gene whose expression defines pathogenic fibroblasts in SSc and idiopathic pulmonary fibrosis (IPF) fibrotic lung specimens and is a marker along with LRRC15 for myofibroblasts across tissues." (PMID 36490328, 2022). "Taken together, our results suggest that Cthrc1+ fibroblasts are pulmonary fibrosis-associated fibroblasts with a highly activated phenotype." (PMID 32317643, 2020). "The data presented here clearly demonstrate that the loss of Cthrc1 is detrimental in pulmonary fibrosis." (PMID 28292882, 2017). "In murine models of pulmonary fibrosis, CTHRC1+ fibroblasts exhibit a heightened migratory ability and high potential for engraftment when transferred to injured lungs, reflecting the high degree of tumor invasion associated with CTHRC1 expression." (PMID 41409095, 2025). "Notably, a subpopulation of CTHRC1-positive pathological fibroblasts was increased in lungs affected by COVID-19 and was associated with the progression of pulmonary fibrosis in COVID-19 patients." (PMID 38891078, 2024). "This recently identified fibroblast subset (defined by high CTHRC1 expression) has been implicated as a key contributor to idiopathic pulmonary fibrosis and may also drive lung fibrosis in COVID-19 patients." (PMID 36228039, 2022). "Since CTHRC1-positive fibroblasts are implicated in the progression of fibrosis in COVID-19 patients, these findings raised the possibility of including pirfenidone within a standard treatment protocol to improve the outcome of post-COVID-19 lung fibrosis patients." (PMID 38891078, 2024). "The invasiveness of these fibroblasts promotes pulmonary fibrosis, further supporting the critical role of CTHRC1+ fibroblasts in IPF pathogenesis." (PMID 41409095, 2025). "The first experimental evidence that CTHRC1 plays a central role in fibrotic pathology was obtained in murine models of lung fibrosis." (PMID 38891078, 2024). "Recent studies have underscored the importance of CTHRC1 in pulmonary fibrosis and its regulatory role in maintaining the integrity of the lung matrix." (PMID 38891078, 2024). "The information discussed in this review highlights the potential of CTHRC1 as a biomarker for the early detection of pulmonary fibrosis and as a possible target for developing novel therapeutic strategies." (PMID 38891078, 2024). "Significantly, recent data from Pliant Therapeutics, which developed bexotegrast, showed that this drug targets a subgroup of CTHRC1-positive myofibroblasts responsible for excessive collagen production in pulmonary fibrosis." (PMID 38891078, 2024). "Analyses using single-cell transcriptomics revealed heterogeneity among fibroblasts present in the fibrotic lungs of both mice and IPF patients and emphasized the pivotal involvement of CTHRC1-positive myofibroblasts in pulmonary fibrosis." (PMID 38891078, 2024). "The elevated expression of CTHRC1 in these profibrotic fibroblasts positions CTHRC1 as a potential pivotal player in the progression of pulmonary fibrosis." (PMID 38891078, 2024). "This review highlights the current evidence linking CTHRC1-positive fibroblasts to the pathogenesis of pulmonary fibrosis." (PMID 38891078, 2024).
pulmonary fibrosis (continued). "An analysis of the human lung revealed five fibroblast subtypes, one of which (CTHRC1+) promotes lung fibrosis in COVID-19 patients." (PMID 35701396, 2022). "Their increased frequency during this period suggested that CTHRC1 + cells were pFBs promoting rapidly evolving lung fibrosis in individuals with COVID-19." (PMID 36405615, 2022). "The Cthrc1+ subset we describe is likely to play an important role in the development of pulmonary fibrosis in mice and humans." (PMID 32317643, 2020). "Single-cell RNA-sequencing of human lungs, including those from idiopathic pulmonary fibrosis and scleroderma patients, demonstrate similar heterogeneity and CTHRC1-expressing fibroblasts present uniquely in fibrotic lungs." (PMID 32317643, 2020). "Only a fraction of COL1A1 and CTHRC1 positive cells co-expressed with ACTA2 (gene of αSMA protein) in human idiopathic pulmonary fibrosis and scleroderma, implying the clinical existence of other ‘non-classic’ fibroblast phenotypes involved in fibrosis." (PMID 33266300, 2020). "The systemic loss of CTHRC1 increased TGF-β1-mediated excess matrix deposition and induced the development of bleomycin-induced lung fibrosis in mice." (PMID 31185973, 2019). "For example, pulmonary fibrosis-associated markers like CTHRC1 were not induced suggesting that pro-inflammatory, mechanical or injury-related cues are necessary to reveal key tissue-specific features." (PMID 40739279, 2025). "Cthrc1+ Fb have traditionally been considered a pathologic collagen-producing subpopulation that emerges in response to bleomycin injury and is overrepresented in human pulmonary fibrosis." (PMID 39836476, 2025). "Furthermore, in pulmonary fibrosis, emerging evidence suggests a pivotal role for CTHRC1 in promoting fibroblast activation, myofibroblast differentiation, and collagen deposition within the lung parenchyma." (PMID 38891078, 2024). "Consequently, the response to pirfenidone treatment can potentially be predicted by evaluating CTHRC1 levels in myofibroblasts, providing an avenue for identifying novel treatment options for lung fibrosis." (PMID 38891078, 2024). "These pFBs are crucial for the development of pulmonary fibrosis, as indicated by robust increases in collagen triple helix repeat containing 1 (CTHRC1) that regulates collagen matrix deposition, and the pathogenic ECM components such as collagen type I alpha 1 chain (COL1A1) and COL3A1." (PMID 38846354, 2024). "Fibroblasts expressing collagen triple‐helix repeat containing 1 (Cthrc1), the marker of pathological fibroblasts in pulmonary fibrosis, express the highest levels of collagen and acquire more migration capabilities than other subsets of collagen‐producing cells." (PMID 38405059, 2024). "Moreover, the elimination of Cthrc1-expressing fibroblasts in lung fibrosis using Cthrc1-CreER mice attenuated hydroxyproline, a marker of collagen deposition, following bleomycin administration." (PMID 38891078, 2024). "Importantly, CTHRC1 has been reported as being involved in the mechanism of action (MoA) of pirfenidone, an anti-fibrotic agent approved for treatment of idiopathic pulmonary fibrosis and an ongoing study showing promising results for heart conditions." (PMID 36531712, 2022). "Furthermore, CTHRC1 is known to participate in the regulation of collagen synthesis and even cardiac and pulmonary fibrosis." (PMID 35937591, 2022). "In this sense, we speculated that NEDD4L may regulate the progression of pulmonary fibrosis through the CTHRC1/HIF-1α signal axis." (PMID 34512149, 2021). "This rather indicated a pro-fibrotic role of CTHRC1 in human pulmonary fibrosis." (PMID 33266300, 2020). "We found that Cthrc1 is a marker for pathologic fibroblasts in pulmonary fibrosis." (PMID 32317643, 2020).
pulmonary fibrosis (continued). "A previous report has shown that CTHRC1 plays a protective role in pulmonary fibrosis and tissue repair and may be clinically applied for treating fibrosis as it decreases collagen matrix deposition by inhibiting Smad2/3 activation." (PMID 31185973, 2019). "Instead, we performed functional experiments in lung fibroblasts and analyzed the responses of fibroblasts derived from patients with lung fibrosis to pirfenidone for determining the utility of CTHRC1 as a potential therapeutic target and predicting pirfenidone responses in lung fibrosis." (PMID 31185973, 2019). "Thus, CTHRC1 can be used for predicting pirfenidone response and developing new therapeutic targets for lung fibrosis." (PMID 31185973, 2019). "We conclude that Cthrc1 plays a protective role, limiting collagen deposition and could form the basis of a novel therapy for pulmonary fibrosis." (PMID 28292882, 2017). "Additionally, Cthrc1 reduced fibrotic tissue formation in bleomycin-induced lung fibrosis." (PMID 41362745, 2026). "Moreover, Cthrc1 ko mice were protected from lung fibrosis following bleomycin treatment." (PMID 37932771, 2023). "Intriguingly, researchers have dissected that expansion of CTHRC1+ pathological lung fibroblasts resulted in rapidly progressing pulmonary fibrosis in patients with COVID-1955, indicating that CTHRC1 might be identified as a novel potential therapeutic target for COVID19 in the future." (PMID 36923925, 2023). "Moreover, it has been established that the Wnt/β-catenin signal axis was activated in pulmonary fibrosis, and β-catenin could bind to the CTHRC1 promoter region." (PMID 34512149, 2021). "Recent research has highlighted the role of CTHRC1, a secreted protein involved in ECM and tissue remodeling, as a biomarker for lung fibrosis and coexpressed proteins as a marker for disease diagnosis and the monitoring of pirfenidone treatment." (PMID 38891078, 2024). "PFD: pirfenidone; IPF: idiopathic pulmonary fibrosis: FVC: forced vital capacity; TGF-β1: transforming growth factor-beta one; CTHRC1: collagen triple helix repeat-containing protein one." (PMID 33564498, 2021). "In humans with pulmonary fibrosis we and others have analyzed, CTHRC1+ fibroblasts emerged in pulmonary fibrosis associated with IPF and scleroderma, suggesting that there might be common mechanisms of fibrosis associated with CTHRC1+ fibroblasts in both diseases." (PMID 32317643, 2020). "More importantly, our finding is demonstrative of Cthrc1's potential as a TGF‐β inhibitor and potential as a therapeutic target for pulmonary fibrosis." (PMID 28292882, 2017). "Of note, in agreement with our data, a recent case has suggested that the level of CTHRC1 was elevated in lung tissues of IPF, and it also indicated that CTHRC1 could promote pulmonary fibrosis through inducing LFs activity." (PMID 34512149, 2021). "Here, we focus on Cthrc1+ fibroblasts, a recently identified sub-type that is not present in normal conditions, but which accumulates at sites of active fibrogenesis in the bleomycin-induced lung fibrosis model and in idiopathic pulmonary fibrosis patients." (PMID 37311583, 2023). "However, in contrast to CTHRC1, FHL2 has been reported to positively regulate the expression of collagen types I and III in an FHL2-induced BLM-treated lung fibrosis model; this process tended to involve acceleration of lung inflammation rather than direct FHL2-induced fibrotic mechanisms." (PMID 31185973, 2019). "To validate our speculation that NEDD4L may modulate pulmonary fibrosis through the CTHRC1/HIF-1α signal axis, we performed Pearson correlation analysis on 35 lung tissue of IPF and revealed the negative correlation between the expression of NEDD4L and CTHRC1." (PMID 34512149, 2021).